RETN (resistin)
Diseases named in the same sentence as RETN in open-access papers (continued):
Sharing a sentence is not in itself a finding about the gene and the disease.
diabetes (continued). "The chronic use of DPP-4 inhibitors has been associated with reduced levels of resistin in mice, however sitagliptin cannot suppress resistin levels in patients with type 2 diabetes mellitus." (PMID 26811539, 2016). "Here, we have found the role of resistin in the activation of RAS in our mouse model which offered another possible explanation for the association of resistin with diabetes and hypertension." (PMID 26917360, 2016). "Serum levels of the adipokine RETN (resistin) positively correlate with mortality risk from diabetes and cardiovascular disease." (PMID 27462403, 2016). "According to multiple regression analysis, the CAVI at follow-up was independently associated with the annual change of the serum resistin level, in addition to age and diabetes mellitus (multivariate model)." (PMID 27649254, 2016). "Our results provide evidence for an association between circulating resistin and mortality risk among high-risk patients as are those with diabetes and coronary artery disease." (PMID 25793385, 2015). "Serum albumin, γ-GTP, leptin, resistin, and hyaluronic acid, as well as the presence of diabetes, were associated with hepatic steatosis (≥5%) in the univariate analysis." (PMID 24524410, 2014). "In particular in this study authors showed that the combination of high resistin and the presence of either diabetes or hypertension increased the risk of ischemic stroke." (PMID 20836881, 2010). "In the stratified analysis, the combination of high serum resistin and either diabetes or hypertension markedly increased the risk of ischemic stroke." (PMID 19922611, 2009). "The combination of high resistin and the presence of either diabetes or hypertension increased the risk of ischemic stroke." (PMID 19922611, 2009). "In the stratified analyses, the combination of high resistin and either diabetes or hypertension markedly increased the risk of ischemic stroke." (PMID 19922611, 2009). "However, more long-term interventional studies in larger sample sizes are needed to fully uncover the cause-effect relationships between resistin levels and diabetes-related periodontitis." (PMID 38149100, 2023). "Furthermore, mouse resistin causes IR and contributes to type 2 diabetes mellitus, while human resistin plays a role in inflammation." (PMID 36235241, 2022). "The authors also evaluated the literature regarding the biomarkers that have been evaluated by MR, and showed that for ferritin, N-terminal pro brain natriuretic peptide (NT-proBNP) and resistin there is published evidence of a causal role for these proteins regarding diabetes." (PMID 31446444, 2019). "Both systemic and adipose tissue resistin are linked to dysglycemia in these individuals and may be a potential biomarker for diabetes in this population." (PMID 30778042, 2019). "High plasma resistin levels have been reported in patients with CVD, indicating that increased resistin may be associated with both diabetes and CVD8." (PMID 26917360, 2016). "In addition to diabetes, elevated levels of resistin are associated with other human diseases, including cardiovascular diseases such as arteriosclerosis and heart failure and cancer." (PMID 26076481, 2015). "In addition A1166C polymorphism of AT1R (angiotensin I receptor) and −420C/G polymorphism of resistin in diabetic patients with CAD revealed significant association with diabetes, P = 0.01 and P = 0.009, respectively." (PMID 26587547, 2015). "To gain insights into the role of resistin in kidney function in diabetes, we investigated whether increased resistin levels are associated with low eGFR in more than 1,500 T2D patients of European ancestry from two different geographical regions." (PMID 25811174, 2015). "Based on multivariate regression analysis that included albumin (≥4.0 g/dl), γ-GTP (≥44 IU/L), leptin (≥8.6 ng/ml), resistin (≥8.8 ng/ml), hyaluronic acid (≥76.4 ng/ml), presence of diabetes, and age (≥55 years), leptin was independently associated with hepatic steatosis." (PMID 24524410, 2014).
diabetes (continued). "Increased resistin levels in periodontitis may thus be considered to pose a risk for diabetes by decreasing the insulin sensitivity." (PMID 24692844, 2014). "The mechanism by which resistin induces ischemic stroke in humans and how resistin interacts with diabetes or hypertension to further increase the risk of ischemic stroke remain unclear." (PMID 19922611, 2009). "Furthermore, the combination of high resistin concentration and the presence of either diabetes or hypertension markedly increased the risk of ischemic stroke." (PMID 19922611, 2009). "The association between quintile of resistin and ischemic stroke remained significant even after adjustment for age, sex, BMI, diabetes, total cholesterol, HDL-cholesterol, systolic blood pressure, ECG abnormalities, current drinking, current smoking, and regular exercise (Model 2)." (PMID 19922611, 2009). "Thus, human resistin could be a potential therapeutic target or a diagnostic marker for the short-term and long-term adverse pregnancy outcomes of diabetes during pregnancy." (PMID 32762639, 2020). "Consequently, the reduced resistin concentration after ARJ consumption might contribute to a lower risk for the development of diabetes." (PMID 23825152, 2013). "Decreasing resistin and increasing glucose-dependent insulinotropic peptide in patients with type 2 diabetes mellitus." (PMID 40308774, 2025). "Background and Objectives: This study aimed to investigate the novel adiponectin–resistin (AR) index as a predictor of the development of metabolic syndrome (MetS) in individuals with type 2 diabetes mellitus (T2DM)." (PMID 39596980, 2024). "Based on empirical evidence, among the adipokines discovered thus far, adiponectin, leptin, resistin, and apelin emerge as the most promising candidates for clinical application, particularly in the realms of myocardial protection and diabetes management." (PMID 39538244, 2024). "Due to the insufficient availability of reliable and comprehensive data on resistin, it cannot be considered as a reliable independent predictor of either diabetes or CVD." (PMID 39538244, 2024). "GCF resistin concentrations were increased in patients with diabetes and periodontitis as compared to individuals with gingivitis." (PMID 37342498, 2023). "Multivariate logistic regression analysis highlighted resistin, diabetes, and body weight as independent predictors of aortic stiffness." (PMID 37763771, 2023). "This group demonstrated higher incidences of diabetes, advanced age, increased body weight, body mass index, body fat mass, systolic and diastolic blood pressure, fasting glucose, and serum resistin levels." (PMID 37763771, 2023). "One such cytokine that gained attention over the years is adipokines such as adiponectin, resistin, and chemerin postulated in diabetes and periodontal diseases for their substantial effects on insulin sensitivity and inflammatory disease process respectively." (PMID 36751175, 2023). "The effect of resistin was even higher for cardiovascular deaths (HR = 2.14; 95% CI 1.13–4.06), being exceeded only by suffering diabetes (HR = 3.04; 95% CI 1.98–4.69) or previous acute coronary syndrome (HR = 3.67; 95% CI 2.18–6.18)." (PMID 36380110, 2022). "The published findings on the link between the resistin (RETN) gene polymorphism and type 2 diabetes mellitus (T2DM) risk are still contradictory." (PMID 36619567, 2022). "The current study aimed to investigate the relationship between leptin and resistin levels with novel refined subgroups in patients with type 2 diabetes mellitus (T2DM)." (PMID 34996484, 2022). "Meta-analyses of the resistin (RETN) -420C/G gene polymorphism and the risk of type 2 diabetes mellitus (T2DM) in subgroups stratified by the patients’ mean age." (PMID 36619567, 2022). "In another study on diabetes patients, an inverse correlation between 25(OH)D and serum resistin was revealed." (PMID 36071429, 2022).
diabetes (continued). "Multiple reports highlighted that resistin is a biomarker of inflammation in diabetes as well as in many other inflammatory conditions, like sepsis, inflammatory bowel disease as well as rheumatoid arthritis." (PMID 34996484, 2022). "There is also evidence that pioglitazone is able to reduce levels of pro-inflammatory cytokines, such as resistin, which has a significant role in cardiovascular diseases, diabetes and the metabolic syndrome." (PMID 36295635, 2022). "Characteristics of the investigated studies on the association between the resistin (RETN) -420C/G gene polymorphism and type 2 diabetes mellitus (T2DM) susceptibility." (PMID 36619567, 2022). "In a recent cross-sectional study, Hayder and Kareem described the possible role of resistin in the iron status pathway in patients with non-insulin-dependent diabetes mellitus and ESRD." (PMID 34442028, 2021). "Another review article showed RETN to be a potential biomarker in the interrelationship between PD and diabetes." (PMID 34721734, 2021). "Serum levels of ANGPTL8, resistin, BMI, blood pressure, duration of diabetes, glycosylated hemoglobin (HbA1c), fasting blood glucose (FPG), hypersensitive C-reactive protein (hs-CRP), lipid profile, liver, and kidney function tests were assessed." (PMID 34603198, 2021). "Patients in the low ABI group were older and had higher resistin levels as well as higher diabetes mellitus, hypertension and habit of smoking, and lower estimated glomerular filtration rate than patients in the normal ABI group." (PMID 34886472, 2021). "Previous studies showed altered angiopoietin-like protein-8 (ANGPTL-8) and resistin circulating levels in type 2 diabetes mellitus (T2DM)." (PMID 34603198, 2021). "Diabetes-related plasma biomarkers insulin, leptin, resistin, and glucagon were significantly reduced by quercetin supplementation." (PMID 34439499, 2021). "Cord blood resistin levels were significantly higher compared to the corresponding maternal blood resistin levels in control and women with diabetes." (PMID 32762639, 2020). "The level of resistin in cord blood of infants born to mothers with diabetes (67.3 ± 48.4 ng/ml, n = 42) were significantly higher (P = 0.03) than those born to control women (50.4 ± 35.2 ng/ml, n = 81)." (PMID 32762639, 2020). "The clinical course of chronic pancreatitis and type 2 diabetes mellitus is characterized by an imbalance in the regulatory function of adipokines, leptin, resistin and adiponectin." (PMID 33456608, 2020). "In accord, we found that cord blood mononuclear cells secreted resistin in response to exposure to high glucose and other diabetes-related factors." (PMID 32762639, 2020). "Comparison of adiponectin/leptin and adiponectin/resistin ratios in newly diagnosed diabetes between normal BMI and obese subgroups." (PMID 32028423, 2020). "Much less is known about fetal resistin levels and current studies examining the fetal levels of resistin in diabetes during pregnancy are inconsistent." (PMID 32762639, 2020). "The aims of the present study are to assess the regulation and function of human resistin in fetal circulation and how it affects placenta in diabetes during pregnancy." (PMID 32762639, 2020). "In obese individuals, decreased levels of adiponectin and elevated levels of resistin are considered to signify the possibility of developing diabetes, even years before the advent of the condition." (PMID 33113859, 2020). "Leptin, adiponectin and resistin levels in the blood serum of patients with chronic pancreatitis and type 2 diabetes mellitus, M±m." (PMID 33456608, 2020). "The production of resistin by fetal mononuclear cells reported here provides evidence for resistin as a link between the inflammatory response and energy metabolism in diabetes during pregnancy." (PMID 32762639, 2020).
diabetes (continued). "Studies in humans have shown that resistin mRNA expression was elevated in female patients with type 2 diabetes mellitus in comparison to healthy women, while the serum concentration of resistin in obese and diabetic patients was significantly increased." (PMID 31013835, 2019). "White adipose is also an endocrine organ that produces many adipokines (e.g., adiponectin, leptin and resistin), which are involved in diabetes and cardiovascular disease." (PMID 31665829, 2019). "This study is the first to show that resistin and FGF23 are significantly associated, even on multiple regression analysis including renal function, PTH, vitamin D status, and markers of diabetes." (PMID 30228288, 2018). "While higher circulating levels of resistin havebeen implicated in the development of IR29 and diabetes, its role in HIVLD is inconclusive." (PMID 29466880, 2018). "Our findings demonstrate that hyperglycemia in cultured myocytes and in vivo in cardiac tissues from animal models of diabetes noticeably promoted resistin expression by inducing NFATc activation which was mitigated by the NFATc inhibitor, VIVIT." (PMID 30353146, 2018). "Similar observations of elevated salivary visfatin and resistin have been reported earlier in chronic periodontitis and diabetes." (PMID 29487749, 2018). "We provide evidence that diabetes or hyperglycemia induces resistin expression through the activation of the transcription factor NFATc." (PMID 30353146, 2018). "The roles of resistin and visfatin in the pathophysiology of many diseases such as diabetes, obesity, immunoinflammatory system impairments, rheumatoid arthritis, and cardiovascular diseases have been demonstrated." (PMID 28018676, 2016). "Several studies revealed increases in TNF-α, resistin, and visfatin levels in various disorders such as cholelithiasis, diabetes, and atherosclerosis." (PMID 28018676, 2016). "In assessment of association between CAD and diabetes in Iranian population the following genes showed significant association: paraoxonase 1, adiponectin, eNOS, CETP, AT1R, resistin, MMP-3, BChE K, Apo E, ACE." (PMID 26587547, 2015). "Zhang and his colleagues reported that serum resistin concentrations in type 2 diabetes mellitus were significantly higher than those in impaired glucose tolerance and in normal glucose tolerance patients." (PMID 26517713, 2015). "Biomarkers like CRP, pentraxin-3, visfatin, cystatin, and resistin were evaluated for their presence in periodontitis relating to chronic kidney diseases and diabetes." (PMID 24692844, 2014). "This review provides an insight into the biological action of resistin and its possible role in periodontitis influenced diabetes mellitus and diabetes induced periodontitis." (PMID 24692844, 2014). "This review is intended to give an insight into the biological action of resistin and its role in periodontitis influenced diabetes mellitus and diabetes induced periodontitis." (PMID 24692844, 2014). "These adipokines including leptin, visfatin, resistin, apelin, vaspin, and retinol binding protein-4 can regulate inflammatory responses and contribute to the pathogenesis of diabetes." (PMID 23772224, 2013). "Analysis investigating the correlation of adipokine levels with HbA1c, diabetes duration, BMI, and age showed a positive correlation between HbA1c and resistin levels (r=0.321, p=0.03)." (PMID 24072088, 2013). "Plasma levels of resistin were higher in patients with diabetes (6,12 ±5,93ng/ml), compared to those with IGT (3,85±2,81ng/ml, p-0,021) and NGM (3,77±3,23, p-0,043)." (PMID 23497617, 2013). "Diabetes enhanced the expression of resistin and DGAT1 in epididymal fat pad (P < 0.05); however, pepino intake significantly suppressed mRNA expression of resistin and DGAT1 in epididymal fat pad (P < 0.05)." (PMID 24527264, 2012). "Saliva resistin levels of T2DM patients are significantly higher than those of non-diabetes mellitus." (PMID 22969799, 2012).
diabetes (continued). "Some reports indicate that circulating adiponectin and resistin levels are reduced in diabetes in line with a recent report demonstrating that higher adiponectin levels are associated with lower BMD." (PMID 22451239, 2012). "If rodents that possess PPARG with Pro12 consume a high-fat diet, the small-sized adipocytes accumulate more fat to change to hypertrophic adipocytes, which secrete factors that promote diabetes mellitus, such as TNFα, resistin and free fatty acids." (PMID 22937051, 2012). "One reason is that resistin levels respond to a particular class of diabetes drugs called thiazolidinediones." (PMID 15578112, 2004). "After adjusting for sex, age, body mass index, smoking, alcohol, exercise, diabetes, and serum creatinine, serum resistin levels were 52.2% higher in individuals with phenotypic frailty than in robust controls (P = 0.001) and showed a positive correlation with the Rockwood FI (P = 0.015)." (PMID 39983655, 2025). "The results suggested that long-term cryopreserved serum samples could be used for future studies of at least adiponectin and resistin, which are closely related to the pathophysiology of diabetes, cardiovascular disease, and other metabolic diseases." (PMID 40813429, 2025). "Of note, the elevated levels of resistin in periodontal disease may highlight its role as a specific and sensitive biomarker in the early detection and intervention of diabetes-related periodontitis." (PMID 38149100, 2023). "Although alterations of serum adipocytokines in thyroid dysfunctions and diabetes mellitus have been previously reported, available data related to chemerin, resistin and visfatin in T2DM coexisting with thyroid dysfunctions, are very limited or have not been studied." (PMID 36830883, 2023). "Moreover, resistin levels declined after childbirth, supporting the conclusion that resistin plays a role in the development of diabetes." (PMID 38004222, 2023). "The development of diabetes under these conditions may be due to the influence of adipokines (leptin and resistin), as they stimulate or reduce the secretion of insulin (a hormone that controls serum glucose levels)." (PMID 36875280, 2023). "The four novel subgroups driven by cluster analysis will unravel the role of resistin in diabetes." (PMID 34996484, 2022). "Secretion of adipokines including leptin and resistin is altered in adipose tissue dysfunction and may contribute to diabetes, which may provide promising novel pharmacological treatment strategies for diabetes." (PMID 34996484, 2022). "Furthermore, we observed a null association between resistin concentrations and CRC risk in subgroup analyses by BMI, hsCRP, C-peptide, and baseline diabetes." (PMID 36428592, 2022). "Notably, adipokines have been proposed as biomarkers of disease in humans, e.g., resistin as a biomarker for diabetes complications related to chronic periodontitis and cardiovascular disease." (PMID 36248900, 2022). "Similarly, a more recent meta-analysis of randomized controlled trials found that GLP-1RAs decrease resistin levels in diabetes." (PMID 34660808, 2021). "In addition, a recent clinical study showed a positive relation between GLP-1 and resistin in diabetes." (PMID 34660808, 2021). "In animals, in two mouse models of type 1 diabetes mellitus, the adipocyte markers, Peroxisome proliferator-activated receptor γ2 (PPARγ2), adipocyte Protein 2 (aP2) and Resistin (RETN) were upregulated in tibia, while Ocn mRNA and osteocalcin serum level decreased." (PMID 33925111, 2021). "No relation was found between canine resistin levels and osteoarthritis, pituitary-dependent hyperadrenocorticism and diabetes mellitus, but resistin levels were significantly higher in dogs with acute pancreatitis or diabetic ketoacidosis compared to healthy dogs." (PMID 33142854, 2020).